BCL2 (BCL2 apoptosis regulator)
Diseases named in the same sentence as BCL2 in open-access papers (continued):
Sharing a sentence is not in itself a finding about the gene and the disease.
multiple myeloma (continued). "Dexamethasone, which is known to enhance the activity of anti‐myeloma therapies, can also increase the dependency of MM cells on BCL‐2 for cell survival and their sensitivity to Ven." (PMID 33368455, 2021). "Mechanically, MM cells survival induced by MDSCs is dependent on AMPK activation, MCL-1 and BCL-2 expression in myeloma cells." (PMID 34095111, 2021). "Venetoclax is a highly selective, potent, oral BCL-2 inhibitor that induces apoptosis in multiple myeloma cell lines and primary multiple myeloma cells." (PMID 34680184, 2021). "BH3-profiling has demonstrated that myeloma cells overexpress anti-apoptotic proteins in a heterogeneous manner, making their dependency on the BCL-2 survival signal rather variable." (PMID 34073976, 2021). "The BCL-2 gene is highly expressed in human myeloma cell lines (HMCL) and is thought to play a role in tumorigenesis." (PMID 35127532, 2021). "In myeloma, the expression of antiapoptotic BCL-2 proteins is elevated, thus promoting MM cells’ survival, although the dependence on BCL-2 for cell survival is heterogeneous from one patient with MM to another." (PMID 34680358, 2021). "Interacting with ferrous ions (Fe2+) and oxygen to produce ROS, DHA has been proven to be active in promoting myeloma cell death, overcoming the Dexamethasone resistance by reverting its action to upregulate the expression of the BCL2 protein." (PMID 33669515, 2021). "For instance, dexamethasone renders myeloma cells more BCL-2 dependent while bortezomib and carfilzomib stimulate expression of the MCL-1 inhibitor NOXA, therefore reducing MCL-1 mediated venetoclax resistance." (PMID 34073976, 2021). "High levels of BCL-XL have been reported in multiple myeloma and correlates with increased chemoresistance, although BCL-2 appears to feature more prominently in this cancer type." (PMID 33799592, 2021). "Although both BCL‐2 and MCL‐1 are necessary for MM survival, most myelomas are dependent on MCL‐1 such that BCL‐2 inhibition alone only yields significant response in a minority of cases." (PMID 35846088, 2021). "BCL-2 and its family members function as critical regulators of apoptosis and have been shown to play critical roles in myeloma survival." (PMID 33922567, 2021). "The growing interest in BCL2 inhibitors for the treatment of multiple myeloma (MM) has led to the need for biomarkers that are able to predict patient’s sensitivity to the drug." (PMID 34638381, 2021). "MM cell lines and patient samples, particularly those with t(11:14), have been shown to be particularly sensitive to Bcl-2 inhibitors, making Bcl-2 a potential target in this subtype of myeloma." (PMID 32246161, 2020). "Multiple myeloma is a plasma cell malignancy that escapes from apoptosis by heterogeneously over-expressing anti-apoptotic BCL2 proteins." (PMID 32371863, 2020). "A preclinical study of venetoclax in multiple myeloma demonstrated that the efficacy of venetoclax is dependent on high expression of BCL2 but also low expression of BCLxL and MCL1." (PMID 35582439, 2020). "Myeloma cells escape to apoptosis by over-expressing anti-apoptotic BCL2 proteins allowing the sequestration of high levels of pro-apoptotic proteins." (PMID 32371863, 2020). "CEBPB, which showed gains in four OAML, functions as transcription factor in myeloid cells, but it also has a pathogenetic role in multiple myelomas, and positively regulates BCL2 in B cells." (PMID 32316399, 2020). "BH3 profiling also allows for the identification of BCL-2 dependence in myeloma cells and to predict the response to venetoclax." (PMID 32183335, 2020). "Bcl‐2 is one of the pro‐survival proteins in the Bcl‐2 protein family and is overexpressed in myeloma cell lines and patients samples." (PMID 32780537, 2020).
multiple myeloma (continued). "Many cancers, including myeloma, frequently escape apoptosis through the upregulation of anti-apoptotic proteins such as bcl2, bclxl and Mcl1; therefore, pyroptosis induction provides an alternate therapeutic option." (PMID 33066043, 2020). "In line with its specific binding to BCL-2, ABT-199 tends to be more efficient in multiple myeloma (MM) with high expression of BCL-2 and less effective in MCL-1 overexpressing MM18." (PMID 32839432, 2020). "We also found that PD-L1+ myeloma cells had more proliferative potential and were resistant to antimyeloma agents, with higher expression levels of Ki-67 and Bcl-2 compared with PD-L1− myeloma cells." (PMID 31842518, 2019). "Accordingly, high BCL-2 relative to low MCL-1 expression was reported to indicate BCL-2 inhibitor sensitivity in multiple myeloma, mantle cell lymphoma and Philadelphia-chromosome positive ALL39–41." (PMID 31358732, 2019). "These new targets to be considered in multiple myeloma treatment are the NOTCHs, BCL2, the IDHs, AR, NF2, Porcupine, the JAKs, MEK1/2 and the Aurora kinases." (PMID 31523388, 2019). "These recent findings are in favor of assessing auranofin in myeloma patients resistant to current therapies as well as resistant to the Bcl2-specific BH3 mimetic venetoclax." (PMID 30895171, 2019). "We have shown that glutamine deprivation results in upregulation of BIM and increased binding of BIM to BCL-2 in multiple myeloma (MM)." (PMID 31405035, 2019). "Genes frequently mutated in DLBCL, FL and/or multiple myelomas (MM) such as BCL6 and BCL2 are found in or near spot K upregulated in healthy B cells and, to a lesser degree, in FL, and downregulated in BL and DLBCL." (PMID 31039827, 2019). "Prima-1Met and auranofin induced Bak/Bax-independent cell death and were efficient in myeloma cells resistant to the Bcl2-specific BH3-mimetic venetoclax." (PMID 30895171, 2019). "The BCL-2/MCL-1 ratio has been proposed as predictor of in vitro sensitivity to navitoclax in human myeloma cell lines." (PMID 29682179, 2018). "Bcl-2 overexpression can also rescue myeloma cells from glucocorticoid-induced apoptosis and confer protection from apoptosis induced by IL-6 deprivation." (PMID 29113343, 2017). "Flavopiridol was also shown to synergistically enhance the anti-myeloma effect of Bcl-2 antagonists, bortezomib and TRAIL, while seliciclib potentiates the anti-myeloma activity of doxorubicin and bortezomib." (PMID 29163849, 2017). "Very recently, a small molecule (BDA-366) that targets the BH4 domain of Bcl-2 has been developed and shown to be effective in lung cancers and multiple myeloma." (PMID 28516063, 2017). "To test the effect of the small molecule BDA-366 as a BCL2 BH4 antagonist on the apoptosis of primary myeloma cells, we treated the whole bone marrow (BM) cells harvested from myeloma patients with BDA-366." (PMID 27049723, 2016). "For example, Bcl-2 and Bik levels are significantly correlated in multiple myeloma cell lines where Bcl-2 inhibits Bik-induced apoptosis." (PMID 27120789, 2016). "B-cell lymphoma-2 (BCL2) protein correlates with the survival and the drug resistance of myeloma cells." (PMID 27049723, 2016). "After BDA-366 treatments at concentration of 0.25 and 0.5μM, phosphorylation of BCL2 significantly decreased in both RPMI8226 and U266 cells, coincident with BDA-366-induced exposure of the BCL2 BH3 domain in the treated myeloma cells." (PMID 27049723, 2016). "The overexpression of Bcl-2 is demonstrated to protect the myeloma cells by bortezomib and to some extent by marizomib too, due to its caspase-9 activation." (PMID 26579531, 2015). "It is also possible that the activation (phosphorylation) of BCL2 in ALDH1+ myeloma cells is a consequence of heightened CIN-NEK2-AKT signaling." (PMID 25230277, 2014). "The Bcl-2 protein, regulated by NF-κB is also highly expressed in myeloma patients and in vitro studies have shown its role in the regulation of chemosensitivity." (PMID 24504138, 2014).
multiple myeloma (continued). "In human xenograft models of small-cell lung cancer, multiple myeloma, lymphoblastic leukaemia, and aggressive B-cell lymphoma, Bcl-2/Bcl-XL inhibitors were previously shown to significantly enhance the efficacy of clinically relevant therapeutic regimens." (PMID 24454684, 2014). "BCL2 is a pro-survival protein that protects myeloma cells from drug-induced death and is often over-expressed in cancer cells exhibiting the CIN phenotype, even though it should be down regulated following drug-dependent mitotic arrest." (PMID 25230277, 2014). "Regardless the up-regulation of anti-apoptotic Bcl-2 proteins in myeloma cells can influence ATO-induced apoptosis and up-regulation of Bfl-1 would be consistent with these findings." (PMID 23285138, 2012). "The effects of BCL2-transfection on CKS1B-shRNA induced myeloma cell growth inhibition and death were evaluated." (PMID 20930946, 2010). "Small BH3 mimetic molecules should be considered for further apoptosis-based therapy in myeloma cells expressing endogenous Bik/Bcl-2 complexes." (PMID 21063407, 2010). "Downregulation of vascular endothelial growth factor (VEGF) beta, IL6 and BCL2 were also evident, as previously identified in human multiple myeloma cells following bortezomib-induced apoptosis." (PMID 17895889, 2007). "We found that Atiprimod downregulated the levels of Bcl-2, Bcl-XL, and Mcl-1, and induced apoptotic cell death in U266-B1 myeloma cells." (PMID 15970928, 2005). "The activation of STAT3 in myeloma cells results in the upregulation of antiapoptotic proteins of the Bcl-2 family, such as Bcl-2, Bcl-XL, and Mcl-1, thus providing MM cells with a survival advantage." (PMID 15970928, 2005). "However, preclinical models have demonstrated that MM treatment results in significant decreases in Bcl-2 and Bcl-xL expression in myeloma cells, while the addition of resistin increases their expression." (PMID 41303900, 2025). "Thus, BCLxL appeared to be as least as important as BCL2 in restricting the full impact of MCL1i in myeloma, as suggested." (PMID 40204951, 2025). "In multiple myeloma, all samples were effectively killed by co-targeting BCL2, BCLxL and MCL1." (PMID 40204951, 2025). "Previous study suggested VEN response correlated with higher bcl-2 expression in multiple myeloma." (PMID 40591114, 2025). "However, several other important questions also remain unanswered regarding the role of BCL-2 inhibition in rare plasma cell dyscrasias, such as AL amyloidosis and PCL." (PMID 40190562, 2025). "Additionally, the ratio of MCL-1 to BCL-2 expression determined the response to VEN in myeloma cell lines." (PMID 39052583, 2024). "Supporting this, it has been shown that myeloma cells exposed to H2O2 in culture increase antiapoptotic BCL2 protein levels, suggesting that at certain levels of it might have a role in promoting MM cell survival." (PMID 38732105, 2024). "However, in multiple myeloma BCL-2 expression is varied significantly across molecular and cytogenetic subgroups in multiple myeloma." (PMID 38025905, 2023). "Conversely, only 20% of myelomas preferentially transmit signals via BCL2 proteins, which could be targeted by venetoclax." (PMID 38136374, 2023). "Some myelomas may also evade apoptosis by uncontrolled transcription of BCL-2 protein, facilitated by gene deletions or the amplification of the miR-17–92 cluster." (PMID 38026941, 2023). "In addition, high MCL1/BCL2 or BCL-XL/BCL2 mRNA ratio indicates that myeloma cells resist venetoclax." (PMID 35799216, 2022). "In addition, in multiple myeloma patients, a correlation is found between expression of Kv1.3 and anti-apoptotic Bcl-2 (Multiple Myeloma HOVON-87/NMSG-18-trail dataset obtained from 180 patients, publicly available)." (PMID 35454865, 2022).
multiple myeloma (continued). "Most of the Bcl-2-targeting agents are in the early stages of clinical development; their optimal usage, as well as the question of how to combine these agents with other myeloma-targeting drugs, is being actively investigated." (PMID 35884390, 2022). "Consequently, efficacy of ABT-199 tends to be higher in Multiple Myeloma with a high ratio of BCL-2 relative to BCL-xL or MCL-1." (PMID 35443750, 2022). "Thus, despite possessing the characteristics of terminally differentiated PCs, venetoclax-sensitive myeloma aberrantly preserves or reactivates aspects of the B-cell program, including dependence on BCL-2 that is normally downregulated during differentiation." (PMID 36071980, 2022). "Moreover, in clinical trials of venetoclax, the ratios of Bcl-2/Mcl-1 and Bcl-2/Bcl-xL transcripts correlated to a greater degree than the level of Bcl-2 mRNA alone with efficiency of venetoclax in multiple myeloma patients." (PMID 35008345, 2021). "Dexamethasone, for example, is leading to Bcl-2 dependence and sensitization to venetoclax in multiple myeloma by altering the balance between pro- and antiapoptotic Bcl-2 protein members (increased Bim and decreased Mcl-1 vs. Bcl-2 upregulation), making Bcl-2 expression essential for survival." (PMID 34063867, 2021). "Furthermore, the modulatory effect on BCL-2 expression by other anti-myeloma therapies highlights the potential benefit of combination therapy." (PMID 34073976, 2021). "Besides, the distribution of BIM among BCL-2 proteins was described to favor BCL-2/BCL-xL co-dependencies in MCL-1 dependent myeloma cells." (PMID 34781947, 2021). "Besides, depsipeptide, as an HDACI, decreases the expression of Bcl-2, Bcl-XL, and Mcl-1 in multiple myeloma cells." (PMID 34903991, 2021). "The overexpression of BCL-2 makes myeloma cells resistant to apoptosis." (PMID 33923357, 2021). "Similarly, in 2013, Chinese scientists supported the efficacy of gossypol in inducing apoptosis in myeloma cells in vitro and in vivo, by the inhibition of BCL-2/BCL-XL and caspase-3 and -9 activation." (PMID 33669515, 2021). "Other haematological malignancies expressing high levels of both Bcl-2 and Mcl-1, such as multiple myeloma, may also benefit from the venetoclax and ATO combination, which needs to be validated in future research." (PMID 33858507, 2021). "Moreover, MMSET is a strong co-activator of NF-κB, and their cooperation activates the expression of downstream genes, including IL-6, IL-8, VEGFA, cyclin D, Bcl-2, and survivin, to protect myeloma cells from chemotherapy-induced apoptosis." (PMID 33420361, 2021). "MDSCs inducing AMPK activation and MCL-1 and BCL-2 expression in myeloma cells." (PMID 34095111, 2021). "The BCL-2 antagonist venetoclax is highly effective in multiple myeloma (MM) patients exhibiting the 11;14 translocation, the mechanistic basis of which is unknown." (PMID 32144272, 2020). "Exosome‐transmitted LINC00461 could promote multiple myeloma cell proliferation and suppress apoptosis by modulating microRNA/BCL‐2 expression." (PMID 32424968, 2020). "Among them, venetoclax is a potent and selective BCL-2 inhibitor, which has demonstrated the strongest clinical activity in mature B-cell malignancies, including chronic lymphoid leukemia, mantle-cell lymphoma, and multiple myeloma." (PMID 32183335, 2020). "The present study aimed to determine whether the combination of BCL2 and MCL1 inhibitors at low doses could be of benefit for myeloma cells beyond the single selective inhibition of BCL2 or MCL1." (PMID 32371863, 2020). "In our study, myeloma cells poorly responding to both BCL2 and MCL1 inhibitors represented around 50% of patient samples, which could be found either at diagnosis or relapse." (PMID 32371863, 2020). "However, studies using cell lines or ex vivo cultures of patient cells treated with venetoclax or ABT-737 have shown that there are also subsets of myeloma cells that are primarily BCL-2-dependent." (PMID 30406027, 2018).
multiple myeloma (continued). "In this study, we first found that BetA could induce PP2A activation in multiple myeloma cells with differential Bcl-2 expression." (PMID 29113343, 2017). "Bcl-2 overexpression is found in the majority of myeloma patients and plasma cell lines." (PMID 29113343, 2017). "Our results suggest that combining inhibition of BCL-2 with drugs that reduce the expression or activity of MCL-1 may prove valuable for targeting auto-reactive or malignant PC in autoimmune disease or multiple myeloma, respectively." (PMID 27560714, 2016). "To examine whether the BH4 antagonist could also induce BCL2 conformational change by exposure of the BH3 domain in primary myeloma cells, we stained BDA-366-treated BM MM cells with anti-BCL2 BH3 domain-specific antibodies." (PMID 27049723, 2016). "A few studies showed that adipocytes could protect myeloma cells from chemotherapy induced apoptosis by increasing expression of Bcl-2 and Pim-2 protein." (PMID 27863383, 2016). "BDA-366-induced robust apoptosis in primary myeloma cells from untreated patients or patients with relapsed/refractory myeloma with varying genetic background further indicates that BDA-366 as a novel BCL2 BH4 antagonist possesses potent therapeutic effect for relapsed/refractory myeloma." (PMID 27049723, 2016). "Interestingly, U0126 treatment down-regulated BCL2 in myeloma cells, suggesting that BCL2 represents a downstream target of the MEK/ERK signaling pathway." (PMID 20930946, 2010). "Targeting STAT3 and MEK/ERK/BCL2 activity by specific inhibitors resulted in significant MM cell death and growth inhibition and their combinations had a synergistic cytotoxic effect on myeloma cells." (PMID 20930946, 2010). "Therefore, small BH3 mimetic molecules should be taken into consideration for further apoptosis-based therapy in myeloma cells that constitutively express endogenous Bik/Bcl-2 complexes." (PMID 21063407, 2010). "Although BCL2-cDNA and CKS1B-shRNA doubly-transfected cells clearly showed cell growth inhibition and death compared with SCR-transfected control cells (p <0 .05), BCL2 transfection partially abrogated myeloma cell growth inhibition and death induced by CKS1B-silencing (p < 0.05)." (PMID 20930946, 2010). "In this study, we investigated the proliferation of myeloma cells under hypoxic conditions, focusing on the expression of the BCL2 gene, the BCL2 family member, BCL2‐like protein 11 (BCL‐2 interacting mediator of cell death: BIM), and BCL2 associated agonist of cell death (BAD)." (PMID 40539846, 2025). "Also, butein has been extensively tested and has been shown to inhibit the expression of Bcl-xL, Bcl-2, cyclin D1, and Mcl-1 in multiple myeloma cell lines (U266), and the expression of cyclin D1, Bcl-2, Bcl-xL, survivin, and VEGF in a liver cancer cell line (HepG2)." (PMID 38539427, 2024). "Notably, there is evidence that BCLAF1 could serve as a strong autophagy inducer by displacing beclin-1 from BCL2 in myeloma cells." (PMID 36418457, 2022). "Although our results demonstrated that BCL-2 inhibitors effectively induce apoptosis in AL amyloidosis clonal plasma cells, we next investigated whether this would continue to be evident in vivo and how this therapy would compare with the standard of care, bortezomib." (PMID 36184661, 2022). "Clinically, venetoclax as a monotherapy is highly efficacious in Chronic Lymphocytic Leukemia (CLL) (that is BCL-2 dependent); however, effective only in a minority contingent of MM, with a recent phase 1 study suggesting only selective efficacy within the 11;14 myeloma patients." (PMID 31405035, 2019). "Furthermore, Atiprimod inhibited signal transducer and activator of transcription (STAT) 3 activation, blocking the signalling pathway of interleukin-6, which contributes to myeloma cell proliferation and survival, and downregulated the antiapoptotic proteins Bcl-2, Bcl-XL, and Mcl-1." (PMID 15970928, 2005).